H4C7 (H4 clustered histone 7)
Description:
Core component of nucleosome. Nucleosomes wrap and compact DNA into chromatin, limiting DNA accessibility to the cellular machineries which require DNA as a template. Histones thereby play a central role in transcription regulation, DNA repair, DNA replication and chromosomal stability. DNA accessibility is regulated via a complex set of post-translational modifications of histones, also called histone code, and nucleosome remodeling (By similarity).
Synonyms: H4/L; H4FL; HIST1H4G
Tractability: PROTAC: ubiquitination databases record sites on it.
Gene: Protein-coding gene on chromosome 6 (26,246,611 to 26,246,996, reverse strand). Ensembl gene ENSG00000275663.
Subcellular location: Nucleus; Chromosome
Gene Ontology:
Molecular function: protein binding; structural constituent of chromatin; DNA binding; protein heterodimerization activity
Biological process: nucleosome assembly
Cellular component: nucleus; chromosome
Genetic constraint (gnomAD): Loss-of-function variants: 7 observed, 5.53 expected, observed/expected ratio (o/e) 1.27, 90% interval 0.7 to 1.89. That is too few expected variants to judge how well the gene tolerates losing a copy. Missense variants: 148 observed, 144.14 expected, observed/expected ratio (o/e) 1.03, 90% interval 0.9 to 1.18. Synonymous variants: 69 observed, 59.24 expected, observed/expected ratio (o/e) 1.16, 90% interval 0.96 to 1.42.
Homologues: Orthologues: chimpanzee H4C7 (91% identical), Caenorhabditis elegans his-1 (84% identical), Caenorhabditis elegans his-14 (84% identical), Caenorhabditis elegans his-18 (84% identical), Caenorhabditis elegans his-31 (84% identical), Caenorhabditis elegans his-37 (84% identical), Caenorhabditis elegans his-38 (84% identical), Caenorhabditis elegans his-46 (84% identical), Caenorhabditis elegans his-5 (84% identical), Caenorhabditis elegans his-50 (84% identical), Caenorhabditis elegans his-60 (84% identical), Caenorhabditis elegans his-64 (84% identical), and 4 more. Paralogues in human: H4C1 (85% identical), H4C11 (85% identical), H4C12 (85% identical), H4C13 (85% identical), H4C14 (85% identical), H4C15 (85% identical), H4C16 (85% identical), H4C2 (85% identical), H4C3 (85% identical), H4C4 (85% identical), H4C5 (85% identical), H4C6 (85% identical), and 2 more.